IL33 (interleukin 33)
Diseases named in the same sentence as IL33 in open-access papers (continued):
Sharing a sentence is not in itself a finding about the gene and the disease.
Pruritus (26 papers, 2012 to 2025). Pruritus is an itch or a sensation that makes a person want to scratch. "In the mechanistic basis of the IL-33/IL-31 axis, IL-33 initiates inflammation, while IL-31 enhances neurons’ sensitivity, causing pruritus." (PMID 41155460, 2025). "Another study found that in patients with AD, the level of lichenification and the intensity of pruritus were both linked with the expression of IL-33 in keratinocytes." (PMID 36983094, 2023). "In another study, chronic itch caused by IL-33/ST2 was mediated by astrocytic JAK2-STAT3 cascades, which stimulated TNF- to sensitize gastrin-releasing peptide GRPR signaling." (PMID 36983094, 2023). "IL-4 and IL-33 are also found to induce the secretion of IL-31, which is one of the elements alongside with the discussed interleukins, causing pruritus in AD and in CTCL—but the data are ambivalent concerning lymphomas." (PMID 34948183, 2021). "Recently, IL-33, one of the IL-1 superfamily cytokines, was identified as a pruritus-associated molecule that excites sensory neurons and mediates itch response." (PMID 32214018, 2020). "Furthermore, IL-33 sensitizes sensory nerves to cause intense pruritus, which contributes to scratching behavior." (PMID 39063153, 2024). "IL-33 causes pruritus via ST2L on sensory neurons in animal models of dry skin." (PMID 39063153, 2024). "In this study, IL-33 levels were found to be reduced in PN and negatively correlated with pruritus severity." (PMID 41268562, 2025). "Targeting the IL-31/IL-33 axis represents an emerging therapeutic option, e.g., nemolizumab (anti-IL-31RA) significantly reduces pruritus and AD symptoms in clinical trials." (PMID 41155460, 2025). "IL-33 induces a type 2 immune response; directly stimulates nerves, resulting in pruritus; and has a well-established role in the pathogenesis of AD." (PMID 38067193, 2023). "Transgenic mice with constitutive epidermal-specific IL-33 expression (IL-33tg) spontaneously develop a progressive, AD-like skin inflammation and pruritus." (PMID 33658996, 2020). "A possible mechanism for this is that IL-33 promotes pruritus via a pathway involving IL-13 production, which may enhance histamine-induced pruritus." (PMID 39063153, 2024). "Furthermore, ILC2 and IL4 are cytokines that both induce pruritus and are stimulated via basophils through the action of IL33." (PMID 36983094, 2023). "This means release of more IL-33, creating a scratch-pruritus cycle." (PMID 35386968, 2021). "This suggests the benefits of revealing the regulatory mechanism of IL-33 expression in keratinocytes, which could enable the control of pruritus and cutaneous inflammation in AD." (PMID 32214018, 2020). "As a result, it has also been proposed that imatinib mesylate might operate as a dose-dependent inducer of chemoattractant substances able to induce pruritus, such as IL-33 and IL-31." (PMID 26316486, 2015). "Together with IL-33, TSLP, and histamine, they trigger the sensation of pruritus either directly on the sensory neurons or by modulating the neural transmission, thereby contributing to chronic itch." (PMID 37108720, 2023). "Histamine, IL-33, IL-31, IL-4, IL-13, and thymic stromal lymphopoietin (TSLP) have been suggested to be mediators of pruritus in AD." (PMID 35163297, 2022). "The activation of IL-33/ST2 signaling and its interaction with primary sensory neurons is a critical component of AD pruritus." (PMID 33658996, 2020). "S. aureus uniquely induces IL-33 release from keratinocytes, disrupting barrier function and potentially contributing to non-atopic itch conditions." (PMID 40869459, 2025). "The IL-33 level correlated with the severity of excoriation and xerosis, but not with the severity of pruritus, erythema, lichenification, edema, crust, and serum IgE or eosinophil levels." (PMID 41155460, 2025). "Compared to healthy controls, patients with pruritic MF, but not MF patients without current pruritus exhibited elevated levels of plasma IL-33 and serum tryptase." (PMID 39068637, 2024).
Pruritus (continued). "The inhibition of JAK ensures the inhibition of receptors; therefore, the subsequent biological effects, from a greater number of cytokines, are variably involved in the pathogenesis of pruritus, not only IL13 and IL4 but also IL31, IL2, IL8, IL25, IL33, IFNγ and thymic stromal lymphoprotein (TSLP)." (PMID 35890180, 2022). "Investigating the relationship between pruritus severity and epidermal IL-33 infiltration may offer a non-invasive method to assess keloid inflammation in the future." (PMID 40230853, 2025).
anaphylaxis (25 papers, 2010 to 2025). An acute hypersensitivity reaction that occurs from exposure to an allergen. "We observed enriched representation of 15 anaphylaxis‐associated pathways and identified 15 genes involved in IgE/FcεRI signaling that were convergently modulated by IFNγ, IL‐33, IL‐4 + IL‐13, and TGFβ." (PMID 40926620, 2025). "We have also shown that mice depleted of UA or deficient in IL-33 were protected from anaphylaxis using an intragastric sensitization protocol with CT." (PMID 29757238, 2018). "Instead, IL33 seems to have a role during early skin inflammation and in driving anaphylaxis, favoring mast cell degranulation." (PMID 37048784, 2023). "Recent reports revealed that IL-33 plays an important role in allergic responses, including the exacerbation of food-induced anaphylaxis in the gastrointestinal tract." (PMID 31611274, 2019). "Recombinant IL-33 has been shown to enhance mast cell responses in murine anaphylactic shock and these authors concluded that IL-33 enhances mast cell reactivity to IgE stimulation." (PMID 20689814, 2010). "Functionally, we demonstrate that the IL-33/ST2 axis is important for the late phase response in a mast cell-dependent model of anaphylaxis by recruiting of inflammatory cells into the site of mast cell activation." (PMID 20689814, 2010). "IL33 signaling through IL1RL1 was shown to be involved in anaphylactic shock in an animal model study examining the response of IgE-sensitized mice to IL33 treatment." (PMID 21629437, 2010). "Functionally, we show that IL-33 is expressed within the skin and is upregulated during IgE-driven anaphylaxis." (PMID 20689814, 2010). "The role of IL-33 was also studied in murine models presenting with FA-induced anaphylaxis." (PMID 31766607, 2019). "However, excessive IL-33 led to allergic inflammation, including airway allergic inflammation and food-induced anaphylaxis." (PMID 29977243, 2018). "Importantly, IL-33 has been reported as critical for Th2 polarization as well as the induction of allergen-specific IgE and anaphylaxis in models of both gut and skin allergic sensitization." (PMID 29757238, 2018). "Interestingly, we have observed differences in the baseline levels of IL-33 within the skin of the different strains of mice studied and yet the changes in the levels of IL-33 induced during anaphylaxis were relatively similar." (PMID 20689814, 2010). "Therefore, therapy targeted to IL-33 blockade might prevent food-induced anaphylaxis in atopic patients." (PMID 31766607, 2019). "The results of our study demonstrate that mast cells express IL-33 and that IL-33 and ST2 are critical for the development of late-phase inflammation occurring during anaphylaxis." (PMID 20689814, 2010). "Our result demonstrated for the first time that IL-33/ST2 signals can trigger anaphylaxis in naïve mice in the absence of specific allergen." (PMID 22702477, 2012). "Data reported in this study reveal a hitherto unrecognized effect and mechanism by which IL-33 induces IgE production and anaphylaxis in the absence of specific allergen." (PMID 22702477, 2012). "Nevertheless, these findings add to the previous data demonstrating that IL-33 acts via ST2 to increase mast cell surface IgE, and to trigger histamine release and systemic anaphylaxis in naïve mice and that poly I:C activates mast cells via TLR3, which may result in the recruitment of CD8+ cells." (PMID 30337928, 2018).
Insulin resistance (25 papers, 2012 to 2025). Increased resistance towards insulin, that is, diminished effectiveness of insulin in reducing blood glucose levels. "The effects of IL-33 on ex vivo glucose uptake by adipocytes were also assessed and shown to have a significant inhibitory effect, indicating a potential role for IL-33 in the development of insulin resistance." (PMID 39171751, 2024). "IL-33 plays protective roles via various mechanisms: it inhibits resistin synthesis and thus inhibits insulin resistance and T2DM development." (PMID 37762140, 2023). "Interleukin-33, as well as ILC2s, has been in the spotlight due to their putative contributions in the improvement of obesity-induced insulin resistance." (PMID 26779183, 2015). "The main finding of this study is that sST2, a decoy receptor for the recently described IL-1 family member IL-33, correlates with classic and novel markers of insulin resistance/endothelial dysfunction." (PMID 23112853, 2012). "Additionally, studies have shown a serial decline in IL-33 levels in DN, resulting in an increased severity of insulin resistance and microalbuminuria." (PMID 36776877, 2023). "Loss of IL-33 or ST2 leads to the dysregulation of homeostatic immune cell balance, characterized by decreased Treg populations in adipose tissue, and manifested in increased weight gain and insulin resistance." (PMID 37197653, 2023). "Thus, treatment with IL-33 ameliorated HFD-induced systemic insulin resistance and glucose intolerance." (PMID 27172901, 2016). "This suggests that IL-33 may play a role in glucose regulation and thus may be involved in the molecular mechanisms that protect against the development of insulin resistance." (PMID 24886535, 2014). "Finally, the loss of type 2 immune subsets, IL-33 responsiveness, and changes in the TRM transcriptional phenotype along with a concomitant increase in M1-like cells, support an increase in inflammation, which has been previously linked to insulin resistance." (PMID 35618862, 2022). "In addition, IL-33-treated mice showed a significant decrease in the severity of HFD-induced insulin resistance and glucose intolerance, which were indicated by changes in plasma levels of glucose in response to a peritoneal injection of insulin and glucose, respectively." (PMID 27172901, 2016). "Together, these studies suggest that loss of VAT Treg cells in high-fat diet feeding leads to increased IL-33 levels in VAT due to unrestrained expansion of IL-33–producing mesenchymal cells, resulting in aberrant inflammation that promotes insulin resistance." (PMID 38668758, 2024). "IL-1, IL-6, IL-17, IL-33, GATA-3, and other proinflammatory cytokines also play important roles in renal insulin resistance." (PMID 36776877, 2023). "IL-33 increases death receptor 3 (DR3) expression on ILC2s and activates the NF-κB pathways, thus stimulating ILC2s and protecting against insulin resistance." (PMID 35574038, 2022). "Accumulating evidence supports the role for IL-33/ST2 axis as a positive regulator of VAT Treg cells by counteracting obesity-induced adipose inflammation and insulin resistance." (PMID 30323806, 2018). "IL-33 can alleviate high-fat diet- (HFD-) induced hepatic steatosis and insulin resistance, and IL-33 acts as an alarmin, which quickly triggers the immune system to respond to virus invasion and toxic damage to the liver." (PMID 29180837, 2017). "IL-33 levels showed a positive correlation with dysglycemia, insulin resistance, and adiposity markers and a negative correlation with gene pathways associated with glucose uptake and lipid storage." (PMID 39171751, 2024). "Systemic administration of IL-33 in mice expanded the pool of ST2+ Treg cells and reversed the obesity-induced diminished Treg pool in adipose tissue, resulting in amelioration of hyperinsulinemia and insulin resistance." (PMID 37197653, 2023).
Insulin resistance (continued). "However, a recent study reported that although administration of IL-33 induced VAT Treg cell expansion, it also promoted insulin resistance." (PMID 30323806, 2018). "Furthermore, treatment with IL-33 alleviated HFD-induced hepatic steatosis, reduced serum alanine aminotransferase (ALT) levels, and ameliorated insulin resistance and glucose intolerance." (PMID 29180837, 2017). "Moreover, treatment with IL-33 restored the ST2-positive Treg population, reduced AT inflammation, and improved insulin resistance." (PMID 26779183, 2015).
ischemic stroke (25 papers, 2013 to 2025). A stroke disorder caused by obstruction of blood flow to the brain, due to thrombotic (local blood clot formation) or embolic (due to a blood clot or other material traveling from another site) event. "A significant relationship was also found between the IL-33 rs7044343 polymorphism and ischemic stroke in a Chinese cohort." (PMID 34177886, 2021). "It turned out that a lower IL‐33 levels are associated with one‐year unfavorable outcome and recurrent ischemic stroke in AIS patients." (PMID 31397082, 2019). "In Cox regression analysis, IL‐33 level was associated with recurrent ischemic stroke with an unadjusted HR 0.980 (95% CI 0.964–0.996, p = .016)." (PMID 31397082, 2019). "We investigated four SNPs in IL33 gene (rs4742170, rs1929992, rs10975519, rs16924159), and discovered two SNPs (rs4742170, rs1929992) were significantly associated with ischemic stroke at univariate analysis." (PMID 24107076, 2013). "Univariate analysis showed two single nucleotide polymorphisms (rs1929992, rs4742170) in IL33 were associated with ischemic stroke in additive, dominant, and recessive model." (PMID 24107076, 2013). "In this study, the IL33 gene polymorphisms associated with history of ischemic stroke in North Chinese patients were evaluated." (PMID 24107076, 2013). "Four polymorphisms (rs1929992, rs10975519, rs4742170, rs16924159) in IL33 gene were selected by Snapshot SNP genotyping assays, and then we analyzed the association between the four SNPs and the risk of ischemic stroke." (PMID 24107076, 2013). "In this study, we reported the significant association of the rs4742170 SNP in IL33 with ischemic stroke in Chinese population for the first time." (PMID 24107076, 2013). "In this sample of patients, genetic variation of rs4742170 in IL33 is significantly associated with the developing of ischemic stroke." (PMID 24107076, 2013). "The long-term protective role of IL-33 in ischemic stroke may be partly associated to its regulation of splenic T-cell immune responses via inhibiting Th1 response and promoting Treg response." (PMID 35173738, 2022). "One recent study showed that the IL-33 gene single nucleotide polymorphism might have a relationship with ischemic stroke in the population residing in the northern part of China." (PMID 27699084, 2016). "Thus, further replication studies will be necessary to evaluate the association between the polymorphisms in IL33 gene and the risk of ischemic stroke." (PMID 24107076, 2013). "The aim of this study was to examine whether the single nucleotide polymorphisms in IL33 are associated with ischemic stroke in Northern Chinese population." (PMID 24107076, 2013). "The risk of ischemic stroke can be influenced by genetic variation in the inflammatory agents, including Interleukin-33 (IL-33), interleukin 4 (IL-4), interleukin 6 (IL-6), intercellular adhesion molecule 1 (ICA M-1), E-selectin (E-sel), chemokine (C-C motif) ligand 11 (CCL11), lymphotoxin (LTA)." (PMID 24107076, 2013). "A study suggests that IL-33 promotes th2-type effects after focal stroke and is neuroprotective, but exacerbates systemic immunosuppression after ischemic stroke." (PMID 38682035, 2024). "IL-33 serves as an independent prognostic marker for both functional outcomes and mortality in patients with ischemic stroke, providing significant additional predictive value beyond the NIHSS clinical score." (PMID 39650246, 2024). "Collectively, we concluded that treatment with GTA improved the BBB repair and functional recovery after ischemic stroke, probably by the enhancement of lipogenesis and IL-33 expression." (PMID 37968698, 2023). "We recently revealed that lipogenesis-mediated interleukin-33 (IL-33) upregulation lead to blood–brain barrier (BBB) repair after ischemic stroke." (PMID 37968698, 2023). "Some traditional oriental medicine, such as celastrol, ameliorate ischemic stroke injury through promoting IL-33/ST2 axis-mediated microglia/macrophage M2 polarization." (PMID 35173738, 2022).